MIR17 (microRNA 17)
Synonyms: hsa-mir-17; MIR17-5p; MIR91; MIRN17; MIRN91; miR-17; miR17-3p; miRNA17; miRNA91
Gene: MicroRNA gene on chromosome 13 (91,350,605 to 91,350,688, forward strand). Ensembl gene ENSG00000284536.
Gene Ontology:
Biological process: miRNA-mediated post-transcriptional gene silencing
Cellular component: RISC complex
Homologues: Orthologues: chimpanzee ptr-mir-17 (100% identical), guinea pig MIR17 (100% identical), macaque mml-mir-17 (100% identical), rabbit MIR17 (100% identical), mouse Mir17 (96% identical), rat Mir17 (93% identical), pig ssc-mir-17 (89% identical), tropical clawed frog xtr-mir-17 (87% identical). Paralogues in human: MIR20B (56% identical), MIR20A (54% identical), MIR106B (52% identical), MIR18A (49% identical).
Diseases named in the same sentence as MIR17 in open-access papers:
MIR17 is named in the same sentence as 7 diseases in open-access papers, as found by Europe PMC text mining. Sharing a sentence is not in itself a finding about the gene and the disease. The quoted sentences say what the papers report.
Feingold syndrome type 2 (1 paper, 2018). Feingold syndrome type 2 (FS2) is a rare inherited malformation syndrome characterized by skeletal abnormalities and mild intellectual disabilities similar to those seen in Feingold syndrome type 1 (FS1) but that lacks the manifestations of gastrointestinal atresia and short palpebral fissures. "Simultaneous deletion of Mir17-92 and Mir106b-25 (doubly conditional knockout, Prx1-Cre:Mir17-92fl/fl:Mir106b-25−/−, 17 dKO) caused microcephaly, cutaneous syndactyly, and brachydactyly, phenotypes similar to those observed in patients with Feingold syndrome type 2." (PMID 29636449, 2018).
multiple system atrophy (1 paper, 2019). Multiple system atrophy (MSA) is a neurodegenerative disorder characterized by autonomic failure (cardiovascular and/or urinary), parkinsonism, cerebellar impairment and corticospinal signs with a median survival of 6-9 years. "Mir-17 is upregulated in the serum of patients with multiple system atrophy." (PMID 31671574, 2019).
Obesity (1 paper, 2021). Accumulation of substantial excess body fat. "The specific knockdown of Mir7 and knockout of Mir17-Mir92 in POMC neurons aggravated diet-induced obesity in females and males, respectively." (PMID 34526970, 2021).
cancer (3 papers, 2021 to 2023). A tumor composed of atypical neoplastic, often pleomorphic cells that invade other tissues. "Studies have shown that the interaction between HCC cells and macrophages can facilitate the proliferation and metastasis of cancer cells through the up-regulation of CXCL8/Mir-17 clusters." (PMID 37400985, 2023). "We selected the MIR17-HG gene, which encodes an oncomir precursor, is a prominent target of MYC in cancer cells, and is activated by TRRAP in HCT116 cells." (PMID 35244540, 2022). "MiRNA MIR17 with low expression could negatively regulate target genes BECN1 and CD28 to promote the proliferation of cancer cells and inhibit autophagy, apoptosis, and the immune response." (PMID 33802957, 2021).
MIR17 also shares sentences with these, for which no sentence is quoted: lung carcinoma (1 paper); microcephaly (1); tumor (1).